CHAF1B (chromatin assembly factor 1 subunit B)
Description:
Acts as a component of the histone chaperone complex chromatin assembly factor 1 (CAF-1), which assembles histone octamers onto DNA during replication and repair. CAF-1 performs the first step of the nucleosome assembly process, bringing newly synthesized histones H3 and H4 to replicating DNA; histones H2A/H2B can bind to this chromatin precursor subsequent to DNA replication to complete the histone octamer.
Synonyms: CAF1A; CAF1P60; MPHOSPH7; MPP7; CAF-1; CAF1; CAF-IP60
Tractability: PROTAC: ubiquitination databases record sites on it.
Gene: Protein-coding gene on chromosome 21 (36,385,354 to 36,419,015, forward strand). Ensembl gene ENSG00000159259.
Subcellular location: Nucleus; Cytoplasm
Subcellular location (Human Protein Atlas): Nucleoplasm
Gene Ontology:
Molecular function: protein binding; chromatin binding; histone binding
Biological process: DNA replication-dependent chromatin assembly
Cellular component: CAF-1 complex; chromatin; cytosol; nucleoplasm; protein-containing complex; cytoplasm; nucleus
Genetic constraint (gnomAD): Loss-of-function variants: 5 observed, 38.95 expected, observed/expected ratio (o/e) 0.13, 90% interval 0.066 to 0.27. The upper end of that interval is the gene's LOEUF score, 0.27, which puts it in group 1 of 6, group 1 being the genes least tolerant of losing a copy. Missense variants: 468 observed, 614.32 expected, observed/expected ratio (o/e) 0.76, 90% interval 0.7 to 0.82. Synonymous variants: 228 observed, 240.06 expected, observed/expected ratio (o/e) 0.95, 90% interval 0.85 to 1.06.
Homologues: Orthologues: chimpanzee CHAF1B (99% identical), macaque CHAF1B (98% identical), dog CHAF1B (88% identical), pig CHAF1B (88% identical), rat Chaf1b (84% identical), mouse Chaf1b (84% identical), guinea pig CHAF1B (78% identical), tropical clawed frog chaf1b (66% identical), zebrafish chaf1b (62% identical), rabbit CHAF1B (61% identical), Drosophila melanogaster Caf1-105 (41% identical), Caenorhabditis elegans chaf-2 (30% identical).
Diseases named in the same sentence as CHAF1B in open-access papers:
CHAF1B is named in the same sentence as 37 diseases in open-access papers, as found by Europe PMC text mining. Sharing a sentence is not in itself a finding about the gene and the disease. The quoted sentences say what the papers report.
breast carcinoma (7 papers, 2019 to 2025). "Consistent with our findings, previous studies have shown that an elevated CHAF1B level was closely associated with a poor prognosis of melanoma, prostate cancer, salivary gland tumors, nasopharyngeal carcinoma, breast cancer, and high-grade glioma." (PMID 33575221, 2020). "The CHAF1B subunit is overexpressed in a variety of tumors, including high-grade glioma, melanomas, prostatic, renal, cervical carcinomas, endometrial tumors, hepatocellular, squamous cell carcinoma, salivary gland tumors, leukemia, and breast cancer." (PMID 35087762, 2021). "CHAF1B mRNA expression is associated with negative oestrogen-receptor status and is significantly lower in the luminal A breast cancer subtype in comparison with luminal B, HER2-positive, and basal-like subtype (BLC) tumours." (PMID 34073937, 2021). "Among the listed genes, BIRC5, SEC14L2, Thymidine kinase (TK1), ZNF385B, CLIC6, ELOVL1, CHAF1B and TFF1 have been reported to have a role in early detection of cancers, tumor progression and metastasis in most of cancer types including breast cancer." (PMID 31703592, 2019). "There were negative expression correlations of hsa-let-7a-5p-CCNB2, hsa-let-7c-5p-CCNB2, hsa-let-7a-5p-AURKB, hsa-miR-30a-5p-CDC20, hsa-miR-30a-5p-MYBL2, hsa-miR-29c-3p-OIP5, hsa-miR-10b-5p-CHAF1B, hsa-miR-195-5p-CCNE1, and hsa-miR-497-5p-CCNE1 in ERα positive breast cancer." (PMID 32500028, 2020).
melanoma (7 papers, 2020 to 2025). A malignant, usually aggressive tumor composed of atypical, neoplastic melanocytes. "Previous studies have shown that elevated CHAF1B levels are closely associated with poor prognosis in patients with many different types of cancer, such as melanoma, prostate cancer, salivary gland tumors, nasopharyngeal carcinoma, and high‐grade glioma." (PMID 41473739, 2025). "In addition, elevated CHAF1B expression has been associated with advanced tumor grade and staging in melanoma, high-grade glioma, salivary gland tumors, prostate, endometrial, renal, and cervical cancers." (PMID 37377894, 2023). "Another example is circ_0079593, which is involved in the development and aggressiveness of melanoma by regulating CHAF1B (Chromatin Assembly Factor 1 Subunit B) and MCAM (Melanoma Cell Adhesion Molecule) genes through the inhibition of miR-516b-5p." (PMID 40869968, 2025). "A subset of MM is characterized by the overexpression of CHAF1B and poly (ADP-ribose) polymerase 1 (PARP-1), another regulator of DNA repair that is associated with aggressive melanoma behaviour." (PMID 34073937, 2021). "The CHAF1B protein is upregulated in malignant melanoma (MM), particularly in the malignant melanocytes of the vertical growth phase." (PMID 34073937, 2021). "In this study, we tested whether circ_0079593 is involved in the progression of melanoma aggressiveness by regulating CHAF1B and MCAM via the inhibition of miR-516b-5p." (PMID 39766913, 2024). "This study aimed to determine whether the circ_0079593, sponging miR-516b-5p, could modify the regulation of two melanoma-associated genes, Melanoma Cell Adhesion Molecule (MCAM) and Chromatin Assembly Factor 1 Subunit B (CHAF1B) in two different types of melanoma metastasis cell lines." (PMID 39766913, 2024). "Among the candidates obtained, MCAM and CHAF1B were found to be the most significantly overexpressed genes in melanoma metastasis cells, along with no miR-516b-5p levels (LM-16) and with high miR-516b-5p levels in LM-36." (PMID 39766913, 2024).
glioma (5 papers, 2020 to 2025). A benign or malignant brain and spinal cord tumor that arises from glial cells (astrocytes, oligodendrocytes, ependymal cells). "It has been confirmed that CHAF1B is overexpressed in laryngeal cancer, squamous cell carcinoma,high-grade gliomas,prostatic cancer and lung cancer, and its high expression leads to a shorter survival period for high-grade gliomas,prostatic cancer and patients lung cancer." (PMID 32508530, 2020).
leukemia (5 papers, 2021 to 2025). A malignant (clonal) hematologic disorder, involving hematopoietic stem cells and characterized by the presence of primitive or atypical myeloid or lymphoid cells in the bone marrow and the blood. "Overall, HMGN1 and CHAF1B block myeloid differentiation and promote leukemia growth in other contexts but their roles in the initiation of TAM and progression to ML-DS are not known." (PMID 36035173, 2022). "CHAF1B is essential for normal hematopoiesis, whereas its overexpression promotes leukemia by binding chromatin at discrete sites and interfering with the occupancy of CCAAT enhancer binding protein alpha (CEBPA)." (PMID 36035173, 2022). "CHAF1B plays a considerable role in leukemia pathogenesis and proliferation of the lung cancer and the prognosis of some cancers." (PMID 33968720, 2021).
prostate carcinoma (5 papers, 2019 to 2025). A carcinoma that arises from epithelial cells of the prostate gland. "Genes, such as CHAF1B, INHBA, TGFB2, SKA3, and HELLS, are responsible for the invasion of various cancer cells, such as hepatocellular carcinoma, gastric cancer cells, renal cell carcinoma, prostate cancer, head and neck cancer, but these genes may be involved in the invasion of BRCA cells." (PMID 31311202, 2019).
hepatocellular carcinoma (4 papers, 2019 to 2025). A malignant tumor that arises from hepatocytes. "However, we found that the autophagy-related gene CHAF1B is a relevant prognostic and diagnostic biomarker in hepatocellular carcinoma." (PMID 33575221, 2020). "When CHAF1B was knocked down, the protein and mRNA levels of TWF2 were considerably reduced in the human hepatocellular carcinoma cell line HUH-7, thus decreasing the invasion and migration of the tumor." (PMID 36128444, 2022).
gastric cancer (3 papers, 2019 to 2025). A primary or metastatic malignant neoplasm involving the stomach. "Using bioinformatics analysis of gastric cancer RNA-seq data from The Cancer Genome Atlas (TCGA) database, we investigated the expression of lnc-CHAF1B-2 in gastric carcinoma and its associated molecular signalling pathways." (PMID 39747989, 2025). "In summary, lnc-CHAF1B-2 played a pivotal role in the progression of gastric cancer and was closely associated with its diagnosis and prognosis." (PMID 39747989, 2025). "By constructing receiver operating characteristic (ROC) curves, we systematically evaluated the potential efficacy of lnc-CHAF1B-2 as a diagnostic biomarker for gastric cancer." (PMID 39747989, 2025). "Next, we analysed the associations between the expression of lnc-CHAF1B-2 and the clinical characteristics of gastric cancer patients." (PMID 39747989, 2025). "The results demonstrated that suppression of lnc-CHAF1B-2 inhibited the proliferation, cell cycle progression, migration, and invasion of gastric cancer cells while promoting apoptosis." (PMID 39747989, 2025). "Conversely, overexpression of lnc-CHAF1B-2 increased the proliferation, cell cycle progression, migration, and invasion of gastric cancer cells and suppressed their apoptosis." (PMID 39747989, 2025). "Bioinformatics analysis revealed that lnc-CHAF1B-2 expression was elevated in gastric cancer tissues and was positively correlated with distant metastases in gastric cancer patients." (PMID 39747989, 2025). "Through Kaplan‒Meier survival analysis, we investigated the associations between the expression levels of lnc-CHAF1B-2 and the overall survival (OS) and disease-specific survival (DSS) of gastric cancer patients." (PMID 39747989, 2025). "In conclusion, lnc-CHAF1B-2 orchestrated gastric cancer development by modulating the activation of the Wnt/β-catenin signalling pathway." (PMID 39747989, 2025). "Through WB analysis, we detected changes in the expression of key proteins in the Wnt/β-catenin signalling pathway in gastric cancer cells following the knockdown and overexpression of lnc-CHAF1B-2." (PMID 39747989, 2025). "We conducted trans-well migration and invasion assays to investigate the influence of lnc-CHAF1B-2 on the migratory and invasive capabilities of gastric cancer cells." (PMID 39747989, 2025). "First, we assessed the impact of lnc-CHAF1B-2 on the proliferation of gastric cancer cells using an EdU assay." (PMID 39747989, 2025). "Thereafter, we employed flow cytometry to assess the impact of lnc-CHAF1B-2 on the apoptosis of gastric cancer cells." (PMID 39747989, 2025). "Mechanistically, lnc-CHAF1B-2 promoted the progression of gastric cancer through activating the Wnt/β-catenin signalling pathway." (PMID 39747989, 2025). "We analysed the impact of lnc-CHAF1B-2 expression on the diagnosis and prognosis of gastric cancer patients." (PMID 39747989, 2025). "In our study, we observed significant upregulation of lnc-CHAF1B-2 expression in gastric cancer tissues." (PMID 39747989, 2025). "Thus, lnc-CHAF1B-2 and its regulation of the Wnt/β-catenin signalling pathway have emerged as prospective therapeutic targets in gastric cancer management." (PMID 39747989, 2025). "We revealed notable upregulation of lnc-CHAF1B-2 in gastric cancer tissues." (PMID 39747989, 2025). "We found that lnc-CHAF1B-2 activated the Wnt/β-catenin signalling pathway, promoting biological processes such as proliferation, cell cycle progression, invasion, and metastasis in gastric cancer cells." (PMID 39747989, 2025). "To further verify the impact of lnc-CHAF1B-2 on the biological behaviour of gastric cancer cells, we used quantitative real-time PCR to detect lnc-CHAF1B-2 expression in five different human gastric cancer cell lines and discovered its presence across all the lines." (PMID 39747989, 2025).
gastric cancer (continued). "Thus, further exploration of the specific regulatory mechanisms of lnc-CHAF1B-2 in gastric cancer cells is imperative to provide valuable insights for gastric cancer treatment." (PMID 39747989, 2025). "However, the specific role and latent mechanisms of lnc-CHAF1B-2 in the malignant progression of gastric cancer necessitate further exploration and research." (PMID 39747989, 2025). "Moreover, our findings confirmed that lnc-CHAF1B-2 enhanced the proliferation, invasion, and migration of gastric cancer cells while inhibiting apoptosis both in vitro and in vivo." (PMID 39747989, 2025). "Based on these findings, we tentatively hypothesized that lnc-CHAF1B-2 might exert its function in gastric cancer through the regulation of the Wnt/β-catenin signalling pathway." (PMID 39747989, 2025). "By exploring the correlation between lnc-CHAF1B-2 and key proteins in Wnt/β-catenin D1, which correspond to the genes CTNN GSK3B and CCND1, we hypothesized that lnc-CHAF1B-2 might promote the development and progression of gastric cancer through activation of the Wnt/β-catenin pathway." (PMID 39747989, 2025). "Taken together, the immune-related lncRNA signature was established with lnc-SLC26A11, lnc-CHAF1B and lnc-PTPA attributing to its prominent prognosis predictive potential in gastric cancer." (PMID 34760687, 2021). "With the help of univariate cox regression analysis, we found that six lncRNAs, lnc-SLC26A11, lnc-CHAF1B-3, lnc-CHAF1B-2, LINC00106, MIR3142HG and lnc-PTPA-3 had significant correlation with prognosis in gastric cancer." (PMID 34760687, 2021). "We subsequently examined the correlation between lnc-CHAF1B-2 expression and the survival and prognosis of gastric cancer patients and discovered a significant negative correlation between lnc-CHAF1B-2 expression levels and patient survival and prognosis." (PMID 39747989, 2025).
cervical cancer (2 papers, 2021 to 2023). A primary or metastatic malignant neoplasm involving the cervix. "Importantly, CHAF1B expression was associated with clinicopathologic data (tumour grade and staging) and was an independent prognostic factor for poor outcome in renal, endometrial, and cervical cancer." (PMID 34073937, 2021). "Similarly with cervical cancer, CHAF1B is a predictor of poor histological grade, advanced stage, and decreased OS in endometrial cancer." (PMID 34073937, 2021). "CHAF1B protein expression is higher in squamous than adenocarcinoma subtypes of cervical cancer." (PMID 34073937, 2021).
colon cancer (2 papers, 2023 to 2025). "In other studies, expression of CHAF1B protein was found to correlate with the proliferation marker Ki-67 in several solid tumors, including breast, prostate, endometrial, cervical, thyroid, renal, gastric, pancreatic, and colon cancers." (PMID 37377894, 2023).
liver cancer (2 papers, 2021 to 2025). An epithelial or non-epithelial malignant neoplasm that arises from the liver. "Consistently, higher ANXA2 and CHAF1B expressions were found in liver cancer specimens by western blot." (PMID 34109194, 2021). "Two key mRNAs (ANXA2 and CHAF1B) were significantly related to liver cancer patients' prognosis, which were both up-regulated in liver cancer tissues in comparison to normal tissues." (PMID 34109194, 2021). "The results showed that ANXA2 and CHAF1B were highly expressed in liver cancer compared to normal specimens, which were consistent with bioinformatics analysis results." (PMID 34109194, 2021). "Using RT-qPCR, we validated the mRNA expression of ANXA2 and CHAF1B in liver cancer." (PMID 34109194, 2021). "For CHAF1B, it has been reported that it can promote liver cancer cell migration." (PMID 34109194, 2021). "Third, although our RT-qPCR and western blot results confirmed that ANXA2 and CHAF1B were highly expressed in liver cancer tissues compared to normal specimens, biological functions and mechanisms of ANXA2 and CHAF1B in liver cancer should be further validated." (PMID 34109194, 2021). "In the ICGC database, our data confirmed that ANXA2 and CHAF1B were both up-regulated in liver cancer in comparison to normal tissues." (PMID 34109194, 2021).
lung adenocarcinoma (2 papers, 2020 to 2025). A carcinoma that arises from the lung and is characterized by the presence of malignant glandular epithelial cells. "Ubiquitin ligase CHAF1B leads to cisplatin resistance in lung adenocarcinoma cells by promoting NCOR2 ubiquitination degradation." (PMID 32508530, 2020). "Our study explored the molecular mechanism of CHAF1B affecting cisplatin resistance in lung adenocarcinoma (LUAD)." (PMID 32508530, 2020). "In this study, we investigated the regulatory mechanism of CHAF1B on cisplatin sensitivity in lung adenocarcinoma, because its effect on IC50 is greater than that of CDC20." (PMID 32508530, 2020). "Gepia suggests that the high expression of CHAF1B is negatively correlated with DFS of patients with lung adenocarcinoma." (PMID 32508530, 2020). "Since PPP1R13L has been reported to be associated with cisplatin resistance and the IC50 decline after knocking down CDC20 was relatively small, this study explored the role of CHAF1B on cisplatin sensitivity in lung adenocarcinoma cells." (PMID 32508530, 2020). "Only NCOR2 and PPP5C met the following requirements: it is down-regulated by more than 1.5 times in A549/DDP, interacts with CHAF1B, has a ubiquitination site and is lowly expressed in lung adenocarcinoma." (PMID 32508530, 2020). "Therefore, our results support that ubiquitin ligase induces cisplatin resistance in lung adenocarcinoma by promoting substrate degradation, and ubiquitin ligases CHAF1B and NCOR2 can be considered as potential biomarkers for cisplatin sensitivity in lung adenocarcinoma." (PMID 32508530, 2020).
Burkitt lymphoma (1 paper, 2023). A rare form of malignant mature B-cell non-Hodgkin lymphoma. "Our results showed that the mRNA and protein levels of DAXX were increased in CHAF1B-depleted cells; comparable results have been reported in Burkitt lymphoma cells." (PMID 37129573, 2023). "Interestingly, a recent study reported the increased transcription of DAXX in CHAF1B-depleted Burkitt lymphoma cells, an observation we confirmed in HeLaCENP-A–TAP cells using RT-qPCR." (PMID 37129573, 2023).
colorectal cancer (1 paper, 2024). A primary or metastatic malignant neoplasm that affects the colon or rectum. "However, there is no information on the role of NAP1L2, TONSL, HDAC9, and CHAF1B in colorectal cancer and were selected for further verification by qRT-PCR." (PMID 38212708, 2024).
cutaneous melanoma (1 paper, 2024). A primary melanoma arising from atypical melanocytes in the skin. "We confirmed that MCAM and CHAF1B were overexpressed compared to the healthy melanocyte cell line (NHEM) in both the commercial cutaneous melanoma cell line (A375) and short-term cutaneous and nodal metastatic melanoma cell lines (LM-36 and LM-16, respectively)." (PMID 39766913, 2024).
esophageal cancer (1 paper, 2025). A primary or metastatic malignant neoplasm involving the esophagus. "However, the exact mechanisms by which MAPK12, CHAF1B, and GABRB3 are involved in the progression of esophageal cancer have not yet been reported in the literature and warrant further exploration." (PMID 41473739, 2025).
metastatic melanoma (1 paper, 2024). A melanoma that has spread from its primary site to another anatomic site. "In conclusion, our results suggest that circ_0079593 can promote the migration of metastatic melanoma cells, increasing aggressiveness, through the regulation of the miR-516b-5p/MCAM and miR-516b-5p/CHAF1B axes." (PMID 39766913, 2024).
mycosis fungoides (1 paper, 2021). Classical mycosis fungoides is the most common type of mycosis fungoides (MF), a form of cutaneous T-cell lymphoma, and is characterized by slow progression from patches to more infiltrated plaques and eventually to tumors. "Recently, it was reported that CHAF1B protein is overexpressed in 27% of mycosis fungoides (MF) patient samples." (PMID 34073937, 2021).